COL5A3 (collagen type V alpha 3 chain)
Description:
Type V collagen is a member of group I collagen (fibrillar forming collagen). It is a minor connective tissue component of nearly ubiquitous distribution. Type V collagen binds to DNA, heparan sulfate, thrombospondin, heparin, and insulin.
Tractability: Antibody: UniProt places it where antibodies can reach, with high confidence; its Gene Ontology location is reachable by antibodies, with high confidence; UniProt predicts a signal peptide or a membrane-spanning region; the Human Protein Atlas places it where antibodies can reach. Other modalities: an approved drug acts on it.
Gene: Protein-coding gene on chromosome 19 (9,959,561 to 10,010,504, reverse strand). Ensembl gene ENSG00000080573.
Subcellular location: Secreted, extracellular space, extracellular matrix; Secreted
Subcellular location (Human Protein Atlas): Plasma membrane; Predicted to be secreted
Pathways (Reactome):
Extracellular matrix organization: Assembly of collagen fibrils and other multimeric structures; Collagen biosynthesis and modifying enzymes; Collagen chain trimerization; Collagen degradation; ECM proteoglycans; Fibronectin matrix formation; Integrin cell surface interactions; Non-integrin membrane-ECM interactions; Syndecan interactions
Developmental Biology: Developmental Lineage of Pancreatic Ductal Cells; NCAM1 interactions
Signal Transduction: MET activates PTK2 signaling; Signaling by PDGF
Disease: Attachment of bacteria to epithelial cells
Gene Ontology:
Molecular function: extracellular matrix structural constituent conferring tensile strength; collagen binding; extracellular matrix structural constituent; heparin binding; proteoglycan binding
Biological process: collagen fibril organization; skeletal system morphogenesis; skin development
Cellular component: extracellular matrix; extracellular region; collagen type V trimer; endoplasmic reticulum lumen
Genetic constraint (gnomAD): Loss-of-function variants: 162 observed, 227.18 expected, observed/expected ratio (o/e) 0.71, 90% interval 0.63 to 0.81. The upper end of that interval is the gene's LOEUF score, 0.81, which puts it in group 3 of 6, group 1 being the genes least tolerant of losing a copy. Missense variants: 2,277 observed, 2,203.7 expected, observed/expected ratio (o/e) 1.03, 90% interval 1 to 1.07. Synonymous variants: 917 observed, 831.92 expected, observed/expected ratio (o/e) 1.1, 90% interval 1.04 to 1.16.
Homologues: Orthologues: chimpanzee COL5A3 (99% identical), macaque COL5A3 (97% identical), dog COL5A3 (89% identical), pig COL5A3 (88% identical), rabbit COL5A3 (87% identical), rat Col5a3 (83% identical), mouse Col5a3 (83% identical). Paralogues in human: COL11A1 (59% identical), COL5A1 (59% identical), COL11A2 (55% identical), COL27A1 (35% identical), COL24A1 (35% identical), COL2A1 (34% identical), COL1A1 (34% identical), COL4A5 (33% identical), COL5A2 (33% identical), COL4A1 (32% identical), COL3A1 (32% identical), COL4A2 (31% identical), and 25 more.
Diseases named in the same sentence as COL5A3 in open-access papers:
COL5A3 is named in the same sentence as 35 diseases in open-access papers, as found by Europe PMC text mining. Sharing a sentence is not in itself a finding about the gene and the disease. The quoted sentences say what the papers report.
breast carcinoma (4 papers, 2017 to 2023). "Gene expression profiling analysis showed that COL5A3 overexpression is related to breast cancer progression." (PMID 33450964, 2021). "Towards this end, effects of ablating the α3(V) gene Col5a3 on mammary tumour biology were studied in the MMTV-PyMT mouse model, which recapitulates many processes observed in human breast cancer progression and metastasis." (PMID 28102194, 2017). "Importantly, COL5A3 has been reported to enhance proliferative potential in breast cancer cells via binding a membrane proteoglycan GPC-1." (PMID 36712590, 2023). "Additionally, BPS upregulates genes (THBS4, PPARGC1A, CREB5, COL5A3) related to breast cancer progression." (PMID 33330580, 2020). "Interestingly, high expression levels for both the α3(V) gene COL5A3 and the GPC1 gene are strongly associated with luminal A breast tumours, with expression level distribution of both genes in human breast cancer in the order luminal A>>luminal B>>basal-like (P<0.0001)." (PMID 28102194, 2017). "However, despite the reduced size of KO/PyMT mammary tumours, Col5a3 ablation did not appear to significantly affect the extent of lung metastasis." (PMID 28102194, 2017).
COVID-19 (3 papers, 2021 to 2023). A disease caused by infection with severe acute respiratory syndrome coronavirus 2. "Interestingly, the decreased level of hsa-miR-29a-3p is negatively associated with COL5A3 in any grade of COVID-19 patients." (PMID 36481664, 2022). "Serum levels of hsa-miR-29a-3p, hsa-miR-31-3p and hsa-miR-126-3p are reduced with increased severity of COVID-19, and the relative expression levels of COL5A3, ZMYM5 and CAMSAP1 are also increased with increased severity of COVID-19." (PMID 37661862, 2023). "Conversely, in COVID-19 patients who respond to treatment (f), the relative expression of ZMYM5, COL5A3, and CAMSAP1 was significantly decreased and the relative expression of DICER1 was significantly increased during hospitalization." (PMID 34256840, 2021). "In COVID-19 patients who did not respond to treatment (e), the relative expression of ZMYM5, COL5A3, and CAMSAP1 was significantly increased and the relative expression of DICER1 was significantly decreased during hospitalization." (PMID 34256840, 2021).
liver fibrosis (3 papers, 2024 to 2025). "Furthermore, the protein–protein interaction (PPI) network analysis based on the STRING database and GOIs provided insights into the functional relationships among key proteins in liver fibrosis, such as Col1a2, Col5a2, MMP9, Col4aa, Col27a1, and Col5a3." (PMID 38874114, 2024).
bladder cancer (2 papers, 2022 to 2025). "In this study, we identified six ECM-related genes (CTHRC1, MMP11, COL10A1, FSTL1, SULF1, and COL5A3) that were associated with bladder cancer occurrence, tumor stage, and prognosis based on the bladder cancer tumor samples." (PMID 35450397, 2022). "Col5a3 was recognized as a hub extracellular matrix (ECM)-related gene, and the elevation of Col5a3 is linked to the development and metastasis of bladder cancer (BLCA)." (PMID 40004494, 2025). "Based on the TCGA dataset, the expression levels of COL10A1, COL5A3, CTHRC1, MMP11, and SULF1 in the bladder cancer tissues were higher than those in the normal bladder tissues." (PMID 35450397, 2022). "CTHRC1, MMP11, and COL5A3 protein levels were increased in bladder cancer than in normal bladder samples." (PMID 35450397, 2022).
oral cancer (2 papers, 2022). "A panel of five genes (MMP1, FBLN5, COL5A3, BGN and LOXL1) was useful for predication the successful grafters among oral cancer patients." (PMID 35444950, 2022).
allergic asthma (1 paper, 2024). A asthma with a basis in a pathological type I hypersensitivity reaction. "Similarly, in eCRSwNP we detected an interaction of basal EpCs with pericyte COL5A2 and COL5A3, both of which have been reported to be differentially methylated in allergic asthma." (PMID 38444858, 2024).
Cirrhosis (1 paper, 2015). A chronic disorder of the liver in which liver tissue becomes scarred and is partially replaced by regenerative nodules and fibrotic tissue resulting in loss of liver function. "Although three other genes (COL4A4, COL6A2, COL5A3) were down-regulated in these patients, our results overall support the notion that white blood cells from patients with cirrhosis are predominately prone to produce collagen." (PMID 26317806, 2015).
glomerulosclerosis (1 paper, 2021). A hardening of the kidney glomerulus caused by scarring of the blood vessels. "As molecular drivers of glomerulosclerosis in diabetic UNx and UNx-Renin mice, our glomerular gene expression analysis confirmed the upregulation of several fibrogenesis-associated genes (e.g. Col1a1, Col5a1, Col5a3, Fn1 and Mmp14)." (PMID 34494644, 2021). "Col5a3, Fn1 and Mmp14 were upregulated in the kidney cortex and glomeruli of UNx-Renin mice compared to both db/m controls and UNx mice, underscoring the advanced progression of glomerulosclerosis in this model of late-stage DKD." (PMID 34494644, 2021).
head and neck squamous cell carcinoma (1 paper, 2024). A squamous cell carcinoma that arises from any of the following anatomic sites: lip and oral cavity, nasal cavity, paranasal sinuses, pharynx, larynx, and salivary glands. "COL5A3 is correlated to BRCA metastasis to the brain and the tumor stemness of head and neck squamous cell carcinoma." (PMID 38601538, 2024).
liver steatosis (1 paper, 2025). "Steatosis severity was associated with upregulation of COL5A3 and TP53I3, whereas upregulated RASGEF1B, S100A12, and TGFBR3 were linked to early-stage liver steatosis." (PMID 40689242, 2025).
lung carcinoma (1 paper, 2022). "Col4a3 expression is associated with the poor prognosis of lung cancer patients after receiving chemotherapy, and Col8a1, Col5a3, and Col15a1 are involved in tumor growth and development." (PMID 35565312, 2022).
melanoma (1 paper, 2024). A malignant, usually aggressive tumor composed of atypical, neoplastic melanocytes. "Transcriptome sequencing of EGR3‐expressing A375 melanoma cells revealed significant up‐regulation of multiple genes associated with the extracellular matrix (ECM), such as COL1A1, COL5A3, and FN1, thereby confirming the regulatory role of EGR3 in the remodeling of the extracellular space." (PMID 38973154, 2024).
metastatic tumor (1 paper, 2022). "COL5A3 is a member of the collagen family and is associated with metastatic tumor growth." (PMID 35450397, 2022).
viral infection (1 paper, 2025). "It is worth noting that genes relating to innate immune response to viral infection (e.g., DHX58, MX1, IFITM-like), cell structure integrity (e.g., ANGPTL3, ANGPTL4, ELFN2, COL5A3) and transcription factors (e.g., TUB) remained upregulated throughout the acute phase of infection (1–6 dpi)." (PMID 40758745, 2025).
tumor (14 papers, 2016 to 2025). "Other notable NET-related CSM and SP genes include previously discussed IGF-2 and IGFBP3 genes and genes related to the stromal component of the tumor (COL5A3, FN1, and NOTCH3)." (PMID 40522948, 2025). "Interestingly, three published gene expression datasets (microarray) also show positive correlations of ETS1 and COL5A3 expression in EWS tumor samples (R>0.7)." (PMID 38187702, 2023). "Survival was markedly increased (P>0.0001, with survival in groups compared using the Log-Rank test) and tumour size markedly decreased in Col5a3−/−, compared with WT, mice injected with WT/PyMT cells, indicating non-cell-autonomous contributions from microenvironments of stromal origin." (PMID 28102194, 2017). "Col5a3−/− MMTV-PyMT tumour cells had greatly reduced proliferative potential, apparently due to loss of interactions between α3(V) and the cell surface proteoglycan glypican-1 (GPC1), affecting ability of the latter to act as a co-receptor for mitogenic factors." (PMID 28102194, 2017). "Interestingly, survival of both WT and Col5a3−/− mice injected with KO/PyMT cells was greatly prolonged up to ∼115 days post injection and tumour growth was greatly delayed, with tumours first palpable at ∼40 days post injection." (PMID 28102194, 2017). "Remarkably, gene expression levels of COL1A1, COL5A3 and TGFB were upregulated (p < 0.05) after the treatment with DPT in Caco-2 cells, another common cell line used to reproduce the features of the tumoural bowel epithelium." (PMID 36012487, 2022). "Here, the expression of COL5A3, FN1, and NOTCH3 was more specific to α-SMA-positive stromal cells rather than tumor cells, while IGFBP3 was overexpressed in both tumor and stroma in comparison to adjacent non-tumor tissues." (PMID 40522948, 2025). "On the other hand, Col4a1, Col4a3, Col4a5, Col5a3, Col11a2, Col14a1, Col15a1, Col16a1, and Col22a1 were found in normal ECM but not in tumor ECM; Col25a1 was found only in tumor ECM but not in normal ECM." (PMID 36547361, 2022).
cancer (7 papers, 2015 to 2023). A tumor composed of atypical neoplastic, often pleomorphic cells that invade other tissues. "Upregulation of collagens, including COL5A3, is a salient feature of fibrosis and malignant tumor stroma, including that in PDAC." (PMID 32660466, 2020). "While COL27A1, COL1A2, and COL5A3 are encoded ECM components, experiments have found that the upregulation of COL1A2 in cancer can serve as a molecular basis for metastasis development." (PMID 31660262, 2019). "The high-throughput proteomics analysis revealed differential expressions of Acsl1, Plin1, Dbil5, Plin4, Col12a1, Col1a1, Col5a3, Col1a2, and Dcn, which are associated with the PPAR signaling pathway, protein digestion and absorption, and the protein glycan pathway in cancer." (PMID 36874004, 2023). "In addition, Col5a3−/− cancer cells injected into Col5a3−/− and Col5a3+/+ mice prolonged survival significantly in both genotypes compared to injection of cells containing the collagen V a3 chain." (PMID 30841909, 2019).
COL5A3 also shares sentences with these, for which no sentence is quoted: pulmonary fibrosis (3 papers); Alzheimer disease (1); atherosclerosis (1); breast tumours (1); central obesity (1); gastric cancer (1); gastric tumors (1); infection (1); Insulin resistance (1); keratoconus (1); lung adenocarcinoma (1); motor neuron disease (1); Obesity (1); ovarian carcinoma (1); sarcoma (1); steatosis (1); type 1 diabetes (1); unipolar depression (1); X-linked ichthyosis (1).